FDX2-ZGLP1 (FDX2-ZGLP1 readthrough (NMD candidate))
Gene: Protein-coding gene on chromosome 19 (10,305,427 to 10,316,009, reverse strand). Ensembl gene ENSG00000167807.
Genetic constraint (gnomAD): Missense variants: 197 observed, 196.43 expected, observed/expected ratio (o/e) 1, 90% interval 0.89 to 1.13. Synonymous variants: 103 observed, 83.97 expected, observed/expected ratio (o/e) 1.23, 90% interval 1.04 to 1.45.